CYBA (cytochrome b-245 alpha chain)
Diseases named in the same sentence as CYBA in open-access papers (continued):
Sharing a sentence is not in itself a finding about the gene and the disease.
myeloma (2 papers, 2011 to 2021). "Moreover, compared to normal bone marrow plasma cells, patients with MGUS, or a smoldering myeloma, NOX2 (encoded by CYBB) is the only catalytic subunit expressed in MM patients along with the p40phox (NCF4) and p22phox (CYBA) regulatory subunits." (PMID 34067602, 2021).
silicosis (2 papers, 2022 to 2024). Silicosis is a respiratory disease caused by breathing in (inhaling) silica dust. "In the present study, lungs of rat model of silicosis showed increased phagocyte NADPH oxidase activity with upregulated five structural components NOX2 (CYBB), p22phox (CYBA), p47phox (NCF1), p67phox (NCF2) and p40phox (NCF4)." (PMID 34991559, 2022).
Achalasia (1 paper, 2023). A disorder of esophageal motility characterized by the inability of the lower esophageal sphincter to relax during swallowing and by inadequate or lacking peristalsis in the lower half of the body of the esophagus. "Analysis of DEGs showed the common upregulations of SFPQ, KLF2, and CYBA and common downregulations of JUNB, FAM118A, and C21orf33 in peripheral blood lymphocytes of achalasia." (PMID 37542039, 2023). "Analysis of DEGs showed the upregulations of PPDPF, NENF, and CYBA and downregulations of FOS, DUSP1, and GPX1 in peripheral blood myeloid cells of achalasia." (PMID 37542039, 2023).
acute kidney injury (1 paper, 2014). Sudden and sustained deterioration of the kidney function characterized by decreased glomerular filtration rate, increased serum creatinine or oliguria. "For example, the variant rs1049255 (G>A) in the 3′ UTR of gene CYBA was reported to be associated with NADPH oxidase (NOX) activity, oxidative stress and acute kidney injury." (PMID 25081214, 2014).
benign prostatic hyperplasia (1 paper, 2017). A non-cancerous nodular enlargement of the prostate gland. "At last, we verified five methylated sites (cg06363129, cg07220448, cg11417025 in SOSTDC1; cg08843517 in CYBA; and cg05385513 in EFEMP1) in PCa and normal tissues, including adjacent tissues and benign prostatic hyperplasia (BPH) through pyrosequencing." (PMID 28938548, 2017).
colorectal adenocarcinoma (1 paper, 2022). The most common type of colorectal carcinoma. "To study the effect of CYBA and TRPM4 on cell proliferation, we knocked down CYBA and TRPM4 with respective siRNAs, separately, in two colorectal adenocarcinoma cell lines, LS174T and HT-29; LS174T is a mucin secreting cell line." (PMID 35158942, 2022).
congenital hypothyroidism (1 paper, 2023). A thyroid hormone deficiency present from birth. "Unsurprisingly, the phenotypes associated with duox and cyba mutations in zebrafish were consistent with mutations in the human orthologs of these genes, with DUOX2 and CYBA, leading to congenital hypothyroidism and chronic granulomatous disease, respectively." (PMID 36843843, 2023).
COVID-19 (1 paper, 2024). A disease caused by infection with severe acute respiratory syndrome coronavirus 2. "S100 proteins are part of the calprotectin dimer, which has been related to COVID-19 severity, and CYBA has been described as an interactor of the Nef protein of HIV-1." (PMID 38778280, 2024).
depression (1 paper, 2022). "For the first time, we discovered that NCF1 and CYBA might be key target genes that explain the role of ERS in the pathogenesis of depression." (PMID 36353576, 2022).
enteropathy (1 paper, 2020). "In five patients we detect a primary immunodeficiency or enteropathy, with clinical consequences (XIAP, CYBA, SH2D1A, PCSK1)." (PMID 32081864, 2020).
esophageal cancer (1 paper, 2022). A primary or metastatic malignant neoplasm involving the esophagus. "The metabolism gene signature, consisting of four shared metabolic hub genes (i.e., FA2H, ICAM1, F3, and CYBA), was further identified to be remarkably elevated in TCGA esophageal cancer tissues compared with combined normal tissues from both TCGA and GTEx dataset." (PMID 36274060, 2022).
Hypercholesterolemia (1 paper, 2021). An increased concentration of cholesterol in the blood. "The CYBA gene encodes the major subunit of nicotinamide adenine dinucleotide phosphate (NADPH), and hypercholesterolemia influences vascular NADPH oxidases." (PMID 34671380, 2021).
kidney cancer (1 paper, 2017). Primary or metastatic malignant neoplasm involving the kidney. "The expression of gene CYBA, a critical component of NOX4 NADPH oxidase complex, was significantly increased by apoptosis in kidney cancers (KIRC)." (PMID 28582771, 2017).
lupus (1 paper, 2025). "Western blot analysis revealed reduced CYBA protein levels in lupus LDGs compared to autologous NDGs or heathy control NDGs." (PMID 41279038, 2025).
mastitis (1 paper, 2024). Inflammation of breast tissue during lactation or postpartum due to an obstructed duct or infection. "The current study showed that bovine neutrophil exposure to minor mastitis-causing bacteria resulted in the upregulation of genes associated with key components involved in ROS generation, with a specific focus on NOX1, CYBA (p22phox), and SOD1 potentially playing a prominent role in this response." (PMID 38922009, 2024).
multiple sclerosis (1 paper, 2025). A progressive autoimmune disorder affecting the central nervous system resulting in demyelination. "Single nucleotide polymorphisms (SNPs) at rs4673 and rs1049254 in CYBA, encoding the NOX2 subunit p22phox, influence NOX2 activity and impact on progression in multiple sclerosis and recovery from Guillain‐Barré syndrome." (PMID 40542608, 2025).
myocardial ischemia (1 paper, 2022). A disorder of cardiac function caused by insufficient blood flow to the muscle tissue of the heart. "In the present study, XML pretreatment was shown to mitigate the upregulation of myocardial ischemia induced by CYBA/CYBB levels." (PMID 35141226, 2022).
promyelocytic leukemia (1 paper, 2019). "These constructs were used to transduce the promyelocytic leukemia cell line PLB-985, which upon differentiation toward a neutrophil-like phenotype expresses all phagocyte NADPH oxidase subunits (including NOX2 and p22phox/CYBA) and produces reactive oxygen species (ROS) through this NADPH oxidase." (PMID 30665184, 2019).
viral infection (1 paper, 2015). "Interestingly, CYBA was recently identified as a host factor implicated in HCV entry in hepatocytes, but the mechanisms underlying its participation in viral infection are currently unknown." (PMID 25888935, 2015).
cancer (24 papers, 2011 to 2025). A tumor composed of atypical neoplastic, often pleomorphic cells that invade other tissues. "NOX1 and NOX4, and the common subunit P22PHOX (encoded by CYBA) are, in contrast, activated in cancer cells and have been associated with keratinocyte-specific activity." (PMID 28122935, 2017). "Additionally, genes that encode for ROS-generating NADPH oxidases (e.g., NOX, CYBA) were also detected using the current pipeline and have been found to play a role in most cancers." (PMID 33143142, 2020). "Targeting CYBA expression or ROS production can provide novel strategies for preventing and treating VTE in high-risk cancer patients." (PMID 40686452, 2025). "Variants in the APCDD1, CYBA, PTK7 and SRC genes were identified in more than one family, and they were shown to dysregulate basic cellular functions, potentially leading to cancer development." (PMID 41469725, 2025). "From this list, 8 novel top candidate genes were selected based on their display of highly cancer-specific hypermethylation over multiple adjacent promoter-associated DMCs: COL4A6, CYBA, HLF, LINC0134 (LOC149234), LRRC4, PROM1, RHCG, and TCAF1 (FAM115A)." (PMID 28052017, 2017). "The significance of CYBA rs4673 differed, but this may be due to differences in the current study’s focus on childhood cancer patients, thus highlighting potential pharmacogenomic distinctions between children and adults." (PMID 40741000, 2025). "CYBB, CYBA, NCF1, NCF2, and RAC2 are NADPH oxidase (NOX) subunit genes and are associated with inflammation and fibrosis in multiple organs, such as the liver, lungs, and kidneys, as well as with various types of cancer." (PMID 37109526, 2023). "Although our data did not allow us to demonstrate a direct mechanism to cancer formation, we showed associations of the CYBA and TRPM4 functions with ROS and mucin production with a likely link to tumorigenesis of CRC." (PMID 35158942, 2022).
tumor (18 papers, 2012 to 2025). "Consistent with previously research, our study also identified upregulation of genes (CP, HP and CYBA) associated with oxidative stress in moderately differentiated tumours." (PMID 40847563, 2025). "CYBA is also involved in the biological processes of angiogenesis and tumor growth by regulating AKT and ERK1/2 signaling pathways." (PMID 28938548, 2017). "Experimental design: Eight novel candidate markers, COL4A6, CYBA, TCAF1 (FAM115A), HLF, LINC01341 (LOC149134), LRRC4, PROM1, and RHCG, were selected from Illumina Infinium HumanMethylation450 BeadChip analysis of 21 tumor (T) and 21 non-malignant (NM) prostate specimens." (PMID 28052017, 2017).
infection (11 papers, 2017 to 2024). The state of being infected such as from the introduction of a foreign agent such as serum, vaccine, antigenic substance or organism. "With wild-type conidia, CybA was detectable at the phagosome only after 1 h of infection, and primarily on near-neutral PLs, while highly acidic phagosomes were generally devoid of CybA." (PMID 32457245, 2020). "A total of 117 cases of infection in the 100 patients were identified (100 associated with CYBB, 10 with CYBA, 3 with NCF1 and 1 with NCF2 mutations), and all had experienced at least 1 infectious episode (IQR 1–3)." (PMID 33168948, 2020). "Infection increased CYBA expression (main effect, p = 0.043)." (PMID 30778359, 2018). "Liver CYBA expression was altered by diet × infection (p = 0.013)." (PMID 30778359, 2018). "At a later stage of infection, the profound effect on host immunity was obvious as subunits of NADPH oxidase (CYBA, NCF2) required for pathogen clearance by phagocytes were enhanced." (PMID 35215144, 2022).
cardiovascular diseases (6 papers, 2012 to 2022). "This is why the genetic polymorphism of the CYBA gene, encoding p22phox, has been of a special interest over almost two decades, especially in the context of cardiovascular disease." (PMID 32423015, 2020). "In recent years, the C242T polymorphism of the CYBA gene has been widely discussed in the context of cardiovascular diseases, however, the results were conflicting." (PMID 22396743, 2012). "Nonetheless, from our analyses of previous studies investigating the association between CYBA gene polymorphisms and cardiovascular disease, it can be seen that the results are not consistent and can even be confusing." (PMID 32423015, 2020).
CYBA also shares sentences with these, for which no sentence is quoted: Stroke (8 papers); colitis (5); diabetic nephropathy (5); immune disorder (4); oral squamous cell carcinoma (4); Cognitive impairment (3); Insulin resistance (3); pulmonary hypertension (3); rheumatoid arthritis (3); thyroid cancer (3); acute myeloid leukemia (2); cardiomyopathy (2); colon cancer (2); diabetic cardiomyopathy (2); essential hypertension (2); fungal infection (2); glioma (2); hearing loss (2); Immunodeficiency (2); intracranial aneurysm (2); ischemic stroke (2); kidney diseases (2); lung carcinoma (2); ovarian carcinoma (2); preeclampsia (2); renal carcinoma (2); renal fibrosis (2); Salmonella Infections (2); steatosis (2); type 2 diabetes (2).
A further 95 diseases each share a sentence with CYBA in 1 paper.